INS (insulin)
Diseases named in the same sentence as INS in open-access papers (continued):
Sharing a sentence is not in itself a finding about the gene and the disease.
Hyperglycemia (continued). "Alternatively, post-operative hyperglycemia may be predominantly driven by factors independent of exogenous corticosteroid, including the physiologic stress response to surgery, medications such as exogenous catecholamines, and relative insulin resistance in the neonatal population." (PMID 37484782, 2023). "While there is a connection between hyperglycemia and SND, a relationship between impaired insulin signaling in the SAN and normoglycemia has never been reported." (PMID 37121973, 2023). "Treatment with PDE4 inhibitors also induces hyperglycemia; however, several lines of evidence suggest that the glycemic effects of PDE4 inhibitors are not predominantly driven by changes in either insulin secretion or signaling." (PMID 36834669, 2023). "Compared with control STAM mice, a significantly higher level of plasma insulin was observed in insulin-treated STAM mice, while no significant induction was detected in PHZ-treated STAM mice, although both treatments ameliorated hyperglycemia significantly." (PMID 37852976, 2023). "In the insulin-responsive 4T1 mouse model of breast cancer, the IGF1R/IR inhibitor BMS-536924 inhibited tumour growth, without significant hyperglycemia." (PMID 36920947, 2023). "However, the impaired insulin secretion by pancreatic β-cell could not overcome the hyperglycemic effects of these counter-regulatory hormones and cytokines, leading to the incidence of stress hyperglycemia." (PMID 37403082, 2023). "The primary cause of the decline in ICC in diabetes was found to be reduced insulin and IGF1 signaling, rather than hyperglycemia." (PMID 37759758, 2023). "Some disadvantages are the lack of alarms during hypoglycemia or hyperglycemia, although the new generation of the FGM will also provide alarms, as well as a lack of interaction with insulin pumps." (PMID 37569354, 2023). "According to the network diagram, no closed loop was formed in the comparison of MBG, hospital length of stay, hyperglycemia, SSI and mean total daily insulin, and a global inconsistency test was not needed." (PMID 37674887, 2023). "The Society of Hospital Medicine and other studies suggested that a simpler insulin therapy regimen than the basal-bolus might be used initially for T2D individuals with good outpatient glycemic control without insulin therapy or with mild inpatient hyperglycemia." (PMID 35758838, 2022). "Supplementation: did not reduce hyperglycemia in rats with induced GDM, but ↑maternal insulin levels and ↓ALT, AST, triglyceride, and total cholesterol levels." (PMID 35052633, 2022). "It has been observed that insulin action is specific in spontaneously hypertensive rats (SHR) and is not related to compensatory hyperinsulinemia or hyperglycemia." (PMID 35455055, 2022). "But there is no universally accepted insulin interventions, a multicenter randomized clinical trial suggested that intensive glucose control in patients with AIS with hyperglycemia did not significant improve functional outcome." (PMID 35645975, 2022). "To validate that insulin, not hyperglycemia, is able to activate the IRE1-XBP1 signaling, we treated 12-h fasted WT mice with 1 U/kg of insulin through intraperitoneal injection, and the liver tissues were collected 15 or 30 min after the insulin injection." (PMID 35863429, 2022). "However, as no hyperglycemia has been reported in female athletes after short-term prednisone treatment, contrarily to their male counterparts, it could be suggested that women are less sensitive than men to the insulin resistance induced by GCs." (PMID 35685685, 2022). "Long-term HMW-IGF-II exposure of pancreatic islet β cells caused the functional impairment, that is, suppressed glucose-stimulated insulin secretion (GSIS), leading to nondiabetic hyperglycemia." (PMID 37908273, 2022).
Hyperglycemia (continued). "The increased risk of fetal macrosomia in GDM mothers is mainly due the following reason: maternal hyperglycemia drives a higher amount of circulating glucose to pass through the placenta and reach the fetal circulation, whereas the maternal-derived or exogenous insulin could not pass the placenta." (PMID 35222271, 2022). "Waiting to see hyperglycaemia (HG) (stage-2/3), in-order to diagnose T2DM, is already deep into pathology progression, where chronic excess insulin levels are no longer able to mask the problem." (PMID 34356863, 2021). "Instead, hyperglycaemia inhibits α cell exocytosis, but not in the T2DM donor’s α cell or when paracrine inhibition by insulin or somatostatin is blocked." (PMID 34502413, 2021). "While in 2D coculture PINP formation was not affected by either high insulin or high glucose, in 3D coculture PINP levels were elevated under hyperglycemia when compared to hyperinsulinemia." (PMID 33805833, 2021). "Plasma insulin and non-esterified fatty acid (NEFA) decreased, and glucose increased during anesthesia in all groups, but hyperglycemia and decrease in NEFA were greater in Me-treated groups." (PMID 35106295, 2021). "STZ-induced low insulin levels and hyperglycemia occurred in both KLK8-/- and KLK8+/+ mice, whereas the levels of insulin and blood glucose in non-diabetic mice were normal." (PMID 33754057, 2021). "By contrast, 1 g/kg α-CD similarly suppressed hyperglycemia, but without increasing secretions of GLP-1 and insulin." (PMID 34639136, 2021). "Automated insulin delivery (AID) systems have been shown to be safe and effective in reducing hyperglycemia and hypoglycemia but are not universally available, accessible, or affordable." (PMID 34096874, 2021). "PG, immunoreactive insulin (IRI), and Pro levels were determined in 1193 young Japanese subjects (<40 years of age) with normal glucose tolerance or nondiabetic hyperglycemia before and at 30, 60, and 120 min during a 75-g OGTT." (PMID 34518649, 2021). "Therefore, once insulin delivery is interrupted for several hours due to pump malfunction, infusion set problems, or manual insulin suspension without giving alternative insulin through injection, acute hyperglycemia, and diabetic ketoacidosis may occur." (PMID 33334003, 2020). "Despite hyperglycemia resulting when VNS, aVNS, and 4 kHz stimulation strategies were applied, the changes in insulin levels were not significant (p ≥ .05)." (PMID 32512650, 2020). "The optimal management of hyperglycemia of diabetic patients infected with SARS-CoV-2 has yet not be defined, however insulin remain the mainstay of treatment approach." (PMID 33066762, 2020). "The significant lower insulin levels and HOMA index in men with the AG genotype compared those with AA suggest a sort of compensatory mechanism to avoid hyperglycemia, which is not observed in men with GG due to the normal glucose levels." (PMID 32681384, 2020). "Given that the effect of GIP on insulin secretion is diminished or absent during hyperglycemia, but our TCF7L2 x GIPR interaction seems to impact insulin secretion during the whole hyperglycemic clamp, a role of an acute GIP effect is not probable." (PMID 30846969, 2019). "As indicated in our results, the transplantation of MSCs alone failed to alleviate the hyperglycemia in T1DM animal models, suggesting that the development from MSCs into insulin-producing cells requires specific triggering factors." (PMID 31438545, 2019). "There were no immunological barriers to efficacy of insulin gene therapy in chemically induced C57BL/6 mice, which enjoyed long-lasting correction of hyperglycaemia after therapy, up to 250 days." (PMID 30514969, 2019). "The in-hospital management of patients with hyperglycemia may affect the development of VT, especially late VT; however, we were unable to examine the impact of anti-hyperglycemic treatment since we did not collect data on the use of insulin or other antidiabetic medications." (PMID 30340589, 2018).
Hyperglycemia (continued). "The GK rat is a polygenic model of type 2 diabetes where β-cell secretory defects result in reduced insulin secretion, impaired GSIS, hepatic insulin resistance, and hyperglycemia in the absence of obesity." (PMID 28542610, 2017). "A recent study demonstrated that brown fat transplantation reduces hyperglycemia in type 1 diabetes in mice, primarily through an increase in circulating IGF-1 and independent of insulin." (PMID 28854965, 2017). "No guidelines exist on how to treat hyperglycemia in patients with GSD-Ia, and while insulin is an obvious option, it can exacerbate hypoglycemia." (PMID 29127952, 2017). "On the other hand, earlier studies showed that serum AGEs are positively correlated with insulin and HOMA-IR in women with PCOS, as long as without hyperglycemia." (PMID 28125989, 2017). "Driving the expression of this construct in the fat body, but not the muscles, intestine, insulin producing cells (IPCs), or AKH-producing cells, disrupts insulin signaling and leads to hyperglycemia." (PMID 27058248, 2016). "MYCL develops on the background of hyperglycemia and hyperinsulinemia combined with increased FFA concentrations, a metabolic condition that is not present in insulin sensitive normal weight subjects." (PMID 26967641, 2016). "Thus, a therapeutic strategy focusing on suppression of postprandial hyperglycemia and improvement of insulin signaling could be a valuable treatment strategy for not only the treatment of diabetic patients, but also individuals with impaired glucose tolerance." (PMID 28035984, 2016). "Pre-meal exercise did not alter insulin-, GIP- and HOMA-IR- lowering effects of low-carbohydrate diet, but exacerbated evening hyperglycemia." (PMID 27798656, 2016). "Surprisingly, the marked and sustained hyperglycemia with VNS (combined afferent and efferent or selective afferent) failed to trigger an increase in serum insulin concentration." (PMID 26884478, 2016). "Although no specific recommendations regarding pasireotide-induced hyperglycemia in patients with acromegaly have been published, treatment with metformin plus a DPP-4 inhibitor, GLP-1 agonist, or insulin would most likely have similar efficacy." (PMID 27405306, 2016). "Other factors that link hyperglycemia to ROP, including low blood IGF-1 level, use of insulin therapy were not addressed in our study." (PMID 25766465, 2015). "Hyperglycemia was observed after glucose treatment in both lines without affecting the phosphorylation of AMPK (cellular energy sensor) and Akt-TOR (insulin signaling) components." (PMID 25141351, 2014). "We show that hyperglycaemia, rather than KATP channel activation per se, accounts for these changes, as they can be prevented by insulin therapy." (PMID 25145789, 2014). "While hyperglycaemia may exacerbate fluid and electrolyte depletion and have a negative effect on endothelial, immune and neurological function, some argue that by allowing vital tissues to utilise glucose independent of insulin some degree of permissive hyperglycaemia may be beneficial." (PMID 24489828, 2014). "In those days, the use of insulin in patients with T2DM was reserved to those individuals who were not able to follow a diet and had severe hyperglycemia." (PMID 24348585, 2013). "Experimentation demonstrated that hyperglycemia was not sufficient to drive glycogen accumulation in IBAT, but that elevated circulating insulin was sufficient." (PMID 23861810, 2013). "This insulin-dependent NET expression and the NA dependency of the spinal nociceptive system support the recent view that hypoinsulinemia itself, rather than hyperglycemia, would play a larger role in the establishment of hyperalgesia." (PMID 24279796, 2013). "Compared to controls (group A), treatment with oral insulin alone (group B), anti-CD20 alone (group C), or the combination (groups D and E) did not induce a significant reversal of hyperglycemia in NOD mice with new-onset diabetes." (PMID 23405091, 2013).
Hyperglycemia (continued). "Insulin therapy is not usually started when T2DM is diagnosed, except where co-morbid conditions or therapy contribute to more extreme hyperglycaemia." (PMID 22519930, 2012). "In contrast, neither hyperglycemia nor hyperlipidemia were observed at varying levels of anemia in animals fed an AIN-93 based diet, although both glucose utilization and insulin responsiveness appeared to be enhanced." (PMID 23110872, 2012). "In order to confirm that the deficits in the axonal transport rates were due to STZ-induced hyperglycemia and not STZ-induced toxicity, we treated the mice with insulin pellets." (PMID 20976160, 2010). "Honey reduced hyperglycemia induced by CUMS, significantly increased serum irisin and non-significantly increased high-density lipoprotein cholesterol (HDL-c) which were decreased by CUMS, but did not affect other serum lipids and insulin." (PMID 40656624, 2025). "Particular attention should be given to patients recently transitioned off insulin or started on SGLT2 inhibitors, as this subgroup may develop ketosis and metabolic acidosis without significant hyperglycemia." (PMID 40376133, 2025). "Where both metformin and insulin are used, they are often introduced in a stepwise fashion such that those requiring insulin have more hyperglycaemia following diagnosis, consistent with having worse GDM-related outcomes to those not requiring additional insulin treatment." (PMID 40559086, 2025). "The use of insulin in children and young adults on CKRT with hyperglycemia has not been studied." (PMID 40272476, 2025). "Whilst there are no head-to-head prospective study comparisons between fixed rate intravenous insulin infusion (FRIII) and VRIII in DKA, VRIII achieved early hyperglycemia correction and DKA resolution without increased hypoglycemia risk in an observational study of 97 patients with DKA." (PMID 40843859, 2025). "The postprandial blood insulin responses (PPIR) were significantly higher after the ingestion of PHs in both the group with and the group without hyperglycaemia, respectively (23.05 mIU/L; 95% CI 7.53, 38.57; p ≤ 0.01 and 12.57 mIU/L; 95% CI 2.72, 22.41; p ≤ 0.01), compared with controls." (PMID 38276562, 2024). "Although classically, insulin and IGF1 have been considered the major link between diabetes and cancer, as opposed to hyperglycemia, recently it has been demonstrated that high glucose levels increase the rate of cell mutation and decrease its capacity for repair." (PMID 38835644, 2024). "In contrast, in animals with glucose infusion hyperglycemia, which present hyperinsulinemia, autophagy markers, including LC3-II/I, ATG7, and BECN1 decreased in gastrocnemius muscle, indicating that insulin in the lack of insulin resistance can suppress autophagy in skeletal muscle." (PMID 37876013, 2023). "In addition, p110α and p110β modulate insulin-driven PI3K/Akt signalling, the inhibition of which would result in hyperglycaemia rather than p110δ and p110γ." (PMID 36773078, 2023). "Regarding insulin regimens using a single daily dose of NPH insulin alone for the treatment of GDM, some experts have reported the efficacy of a bedtime NPH regimen for women with fasting hyperglycemia, as expert opinions without clinical evidence." (PMID 37283948, 2023). "Notably, pretreatment with insulin or metformin did not modify the decreased secretion of TNF-α and IL-6 observed under hyperglycemia." (PMID 36982317, 2023). "Since ASI monotherapies have not effectively reversed hyperglycemia in NOD mice after T1D onset, we combined PPIL4-20 or insulin B9-23 ASI with a suboptimal dose of oral GABA in order to functionally evaluate the ability of insulin B9-23 vs. PPIL4-20 to promote ß-cell tolerance." (PMID 35406645, 2022). "Moreover, regulation of hyperglycemia with insulin seems to be independent of the effects of the OGF-OGFr pathway as both T1D and T1D-INS rats had elevated serum levels of OGF, and both groups responded to blockade of the regulatory pathway with NTX." (PMID 36274979, 2022).
Hyperglycemia (continued). "We found that cardiac and renal CX3CL1 protein levels were significantly increased in both streptozotocin-induced diabetic mice and in non-obese diabetic mice, and that hyperglycemia led to persistent CX3CL1 expression in the heart and kidneys even after it was controlled by insulin." (PMID 35370759, 2022). "In fact, when there are physiological variations towards hyperglycemia, the upper IOB limit (which is constant) could not be enough to allow the required insulin doses, and then prolonged hyperglycemia occurs." (PMID 35265035, 2022). "During insulin-resistant status such as T2DM, insulin fails to inhibit hepatic glucose generation but potentiates lipid synthesis resulting in hypertriglyceridemia and hyperglycemia." (PMID 36127704, 2022). "Although the effect of hyperglycemia on HIF-1α and select NER proteins in our db/db mice mimicked that observed in cells cultured without exogenous insulin, a potential confounding effect of hyperinsulinemia on NER protein expression in this T2D model cannot be ruled out." (PMID 34426491, 2021). "In a sub-group with hyperglycaemia (n = 196), mean age of 41.8 (SD 10.8) years, and with 63.8% being women (background characteristics shown in S1 Table), the same analyses showed similar results except for lack of correlation between HDL with DBP and insulin." (PMID 33630976, 2021). "This safety and performance study was limited by use of an experimental protocol that was not an adequate substitute for the stress induced hyperglycemia experienced by ICU patients, and in addition used overdoses of both insulin and glucose that have no clinical correlate." (PMID 32006145, 2021). "In the event of hyperglycemia with Peg-ASP and steroid therapy, it may be appropriate to reduce the steroid dose and enhance the insulin therapy rather than delay subsequent administrations of Peg-ASP." (PMID 33008391, 2020). "This novel approach to management of glucocorticoid-induced hyperglycemia has not been tested before and if SGLT2 inhibition with empagliflozin compared to NPH insulin is a safe, effective and resource sparing treatment for GIDM, it has the potential to improve the situation for affected patients." (PMID 32539810, 2020). "Current data demonstrate that treatment of hyperglycemia with insulin during CABG surgery can lead to postoperative hypoglycemia and does not always prevent hyperglycemia, especially when selecting a tight blood glucose target, such as 80-110 mg/dl (4.4-6.1 mmol/l)." (PMID 33118731, 2020). "The highest tertile of cystain C was associated with the high proportions of men, smoking, lack of physical activity, hyperglycemia, hypertriglyceridemia, hypertension, low HDL cholesterol, and high mean values of age, fasting insulin, hs-CRP, carotid IMT-mean, and IMT-maximum." (PMID 33129312, 2020). "However, in the condition of reduced insulin sensitivity and decreased BCF, in which β-cells are not able to secrete sufficient insulin, hyperglycemia arises, which eventually results in prediabetes or T2DM." (PMID 29525890, 2019). "However, because of insulin overproduction, most OZR do not present with severe fasting hyperglycemia until they become significantly older than matched ZDF." (PMID 31652915, 2019). "Although adolescent drug use did not interact with the HFD to worsen hyperglycemia and hyperinsulinemia during an OGTT, HFD-fed rats that co-used alcohol and THC had the lowest insulin levels 75 min after an insulin injection, suggesting an altered rate of insulin secretion and degradation." (PMID 31427627, 2019). "DIO mice do not manifest fasting hyperglycemia but have elevated insulin, and after treatment with SA2 (3 mg/kg) for 4 weeks, when measured 18h post dose, there was a significant reduction in plasma insulin and a trend towards decreased fasting plasma glucose." (PMID 30811418, 2019).